FLNA (filamin A)
Diseases named in the same sentence as FLNA in open-access papers (continued):
Sharing a sentence is not in itself a finding about the gene and the disease.
hepatocellular carcinoma (9 papers, 2013 to 2026). A malignant tumor that arises from hepatocytes. "FLNA acts as a pro-oncoprotein in various human malignancies, including metastatic melanoma and hepatocellular carcinoma." (PMID 36105798, 2022). "For example, the expression of FLNa protein was higher in hepatocellular carcinoma HCCLM9 cells with high metastatic potential compared with hepatocellular carcinoma MHCC97L cells with low metastatic potential." (PMID 24137390, 2013). "FLNA is associated with cell proliferation and invasion in hepatocellular carcinoma, while TLN1 participates in the invasion of ovarian serous carcinoma and is active in hepatocellular carcinoma cells." (PMID 30984788, 2019). "In support of the hypothesis that filamin-A promotes cancer metastasis, a comparative proteomic study has identified that high levels of filamin-A were correlated with increased metastatic potential of hepatocellular carcinoma." (PMID 23388158, 2013). "Regarding APOJ, it has also been found that the combination of filamin-A and APOJ genes could potentially serve as a useful marker for hepatocellular carcinoma." (PMID 38067270, 2023). "Our data showed that Sema3d restrained hepatocellular carcinoma proliferation, invasion, and metastasis through inactivating Pi3k/Akt via interaction with FLNA, which may serve as a novel prognostic predictor and a potential therapeutic target for HCC patients." (PMID 35957887, 2022).
Intellectual disability (9 papers, 2011 to 2025). "Mutations in filamin A also induce a wide spectrum of diseases including skeletal dysplasia, neuronal migration abnormality, cardiovascular malformation, intellectual disability, and intestinal obstruction." (PMID 39193363, 2024). "Deletion or duplication of the FLNA gene can affect close genes on the X chromosome, leading to a number of other signs and symptoms, such as neurological abnormalities and intellectual disability." (PMID 38383389, 2024). "In addition, despite no reports of intellectual disability in patients carrying FLNA mutation, there are several reports of intellectual disability in cases with MAP3K7 mutation." (PMID 34716296, 2021).
atherosclerosis (8 papers, 2020 to 2025). A disease characterized by the build-up of fatty material and calcium deposition in the arterial wall resulting in partial or complete occlusion of the arterial lumen. "The C-terminal fragment of filamin A is also implicated in atherosclerosis." (PMID 38958472, 2024). "Additionally, in the late stages of atherosclerosis, it has been demonstrated that macrophages have increased expression of filamin A (FLNA), which is an actin binding protein linked to cell architecture and signaling pathways." (PMID 35884884, 2022). "The pro-atherosclerosis or anti-atherosclerosis effects of many regulatory genes, such as FLNA and SOX2, depend on their location." (PMID 40176913, 2025). "In this context, attenuation of filamin A cleavage following pharmacological inhibition of calpain impaired macrophage signalling and reduced atherosclerosis in mouse models where atherogenesis had been induced by hypercholesterolaemia." (PMID 38958472, 2024). "In this review, we updated some novel functions of FLNA, particularly related to cardiovascular remodeling after MI and atherosclerosis." (PMID 34207234, 2021). "More recently, it was shown that FLNA mediates the progression of myocardial infarction and atherosclerosis." (PMID 34207234, 2021). "We have recently reported that genetic inactivation of FLNA and chemical inhibition of calpain-dependent cleavage of FLNA impairs macrophage signaling and function, and reduces atherosclerosis in mice." (PMID 32941503, 2020). "FLNA, a large actin-binding cytoskeletal protein that is important for cell motility by stabilizing actin networks, has been shown to mediate the progression of myocardial infarction and atherosclerosis." (PMID 39701955, 2024). "Moreover, we found that RAC1 interacts with actin-binding filamin A. Macrophages expressed increased RAC1 levels in advanced human atherosclerosis." (PMID 32941503, 2020). "However, the role of FLNA in atherosclerosis depends on its location." (PMID 40176913, 2025). "We deleted FLNA in macrophages and observed no phenotype in the mice, but when atherosclerosis is induced as a result of a western diet, mice deficient in FLNA in macrophages develop smaller plaques, due to impaired macrophage cell migration, lipid uptake and cytokine response." (PMID 34207234, 2021). "Taken together, the downstream genes of ARL4C, including ABCA1, ALDH1A3, ARF6, ENHO, FLNA, LRP6, OSBPL5, Snail2, and SOX2 play an important role in atherosclerosis." (PMID 40176913, 2025). "Interestingly, FLNA interacts with RAC1 in macrophages and protects against atherosclerosis." (PMID 34207234, 2021). "Furthermore, cytoskeletal FLNACT produced by calpain cleavage physically interacted with RAC1 and we have previously shown that lack of FLNA reduces macrophage activity and atherosclerosis." (PMID 32941503, 2020).
colon cancer (8 papers, 2014 to 2025). "Additionally, WTAP upregulation in colon cancer downregulates FLNA expression through m6A modification at the 3'UTR region." (PMID 41367384, 2025). "Six genes (aldehyde dehydrogenase 2, neural precursor cell expressed, developmentally down-regulated 9, filamin A, lamin B receptor, twinfilin actin binding protein 1, serine and arginine rich splicing factor 1) were closely related to the OS of colon cancer patients." (PMID 30155352, 2018).
Hypertension (8 papers, 2020 to 2024). The presence of chronic increased pressure in the systemic arterial system. "Future studies are necessary to determine whether the association between the NCC and filamin A are augmented in hypertension and if this association inhibits the recycling or degradation of the NCC through the proteasomal pathway." (PMID 34943250, 2021). "Chunlan Liu and colleagues explored the associations of Filamin A (FLNA) and Filamin B (FLNB) variants with hypertension." (PMID 36672629, 2023). "Just replacing one of the PIEZO alleles in these unprotected cells was enough to reverse the increase in wall thickness seen from hypertension or the removal of the FlnA." (PMID 34178967, 2021). "FLNA rs2070816 (CT + TT vs. CC) and rs2070829 (CG + GG vs. CC) were significantly associated with the hypertensive status in young subjects (<55 years group) and FLNB rs839240 (AG + GG vs. AA) was significantly associated with hypertension in females." (PMID 36672629, 2023). "Moreover, based on the decreased A-to-I editing rate of myocardial filamin B, the authors hypothesized filamin B editing to play a still-hidden function in cardiovascular system, similarly as filamin A (FLNA) has been unveiled in hypertension." (PMID 35991314, 2022). "In human macrophages, FLNA expression is higher in advanced atherosclerotic plaques compared with intermediary plaques and inhibition of FLNA expression in mice reduced plaque development, suggesting a role for this gene and the actin cytoskeleton in hypertension-related CVDs." (PMID 32443852, 2020). "For example, proteins important for vascular structure (FLNA) and calcium regulation (ACTN4) were up-regulated, and mitochondrial function (COX6B1) was down-regulated, in human hypertension." (PMID 38879891, 2024). "Studies showed that biomarkers include PLD2, FLNA (filamin A), SMURF1, LINGO1, CACNA1H, NLRP6, NLRC3, CXCR2 and C5AR1 plays an important role in progression of hypertension." (PMID 36837510, 2023).
myocardial infarction (8 papers, 2018 to 2024). Gross necrosis of the myocardium, as a result of interruption of the blood supply to the area, as in coronary thrombosis. "Inhibition of FlnA interaction with Drp1, a modulator of mitochondrial dynamics, attenuates cardiomyocyte senescence after myocardial infarction and involvement of FlnA in thrombotic or bleeding disorders associated with aging has been previously reported." (PMID 38040692, 2023). "FLNA is expressed in human and mouse endothelial cells after myocardial infarction." (PMID 32443852, 2020). "A recent study has also shown that filamin A, through its interaction with Drp1 (modulator of mitochondrial dynamics), attenuates the mitochondrial hyperfission and cardiomyocytes' senescence in an animal model of myocardial infarction." (PMID 30697201, 2018).
Alzheimer disease (7 papers, 2017 to 2025). A progressive, neurodegenerative disease characterized by loss of function and death of nerve cells in several areas of the brain leading to loss of cognitive function such as memory and language. "By restoring the native conformation of FlnA, the small molecule PTI-125 improves the synaptic plasticity in Alzheimer’s disease mouse model." (PMID 38040692, 2023).
gastric cancer (7 papers, 2018 to 2025). A primary or metastatic malignant neoplasm involving the stomach. "Using yeast two-hybrid screening, they reported key regulatory roles for RhoGDIβ in promoting an interaction between Rac1 and Filamin A and the associated activation of Rac1 in the invasiveness of gastric cancer cells." (PMID 40710299, 2025). "We also found that higher expression of both RhoGDI2 and FLNA was associated with poor prognosis in gastric cancer patients." (PMID 35008419, 2022). "A significant reduction in the migration and invasion ability of RhoGDIβ-expressing gastric cancer cells following the depletion of Filamin A was also observed." (PMID 40710299, 2025). "All of our results clearly suggest that RhoGDI2 plays an important role in the interaction between Rac1 and Filamin A and Rac1 activation in gastric cancer cells." (PMID 35008419, 2022). "The migration and invasion ability of RhoGDI2-expressing gastric cancer cells also substantially decreased when Filamin A expression was depleted." (PMID 35008419, 2022). "We have identified the precise molecular mechanism by which RhoGDI2 recruits Rac1 to FLNA and increases Rac1 activity, which is critical for gastric cancer metastasis." (PMID 35008419, 2022). "Conclusively, RhoGDI2 increases Rac1 activity by recruiting Rac1 to Filamin A and enhancing the interaction between Rac1 and Trio, which is critical for invasive ability of gastric cancer cells." (PMID 35008419, 2022). "Depletion of Filamin A expression markedly reduced Rac1 activity in RhoGDI2-expressing gastric cancer cells." (PMID 35008419, 2022). "To explore the role of filamin A in the cell cycle, we silenced the expression of filamin A in gastric cancer cell SGC‐7901 and then treated them with ATPR." (PMID 29862660, 2018). "We also examined the expression of filamin A in these tissues, and we found its level higher in gastric cancer tissues compared with that of the adjacent tissues." (PMID 29862660, 2018). "Immunohistochemical analysis showed that the expression levels of 14‐3‐3ε and filamin A in gastric cancer tissues were significantly higher, with a predominant localization in the cytoplasm, compared to the levels in matched tissues." (PMID 29862660, 2018). "Next, we investigated whether RhoGDI2 could enhance the interaction between Rac1 and FLNA in gastric cancer cells." (PMID 35008419, 2022). "In this study, to identify the precise molecular mechanism by which RhoGDI2 activates Rac1 activity, we performed two-hybrid screenings using yeast and found that RhoGDI2 plays an important role in the interaction between Rac1, Filamin A and Rac1 activation in gastric cancer cells." (PMID 35008419, 2022). "Therefore, we conclude that RhoGDI2 increases Rac1 activity by recruiting Rac1 to Filamin A and enhancing the interaction between Rac1 and Trio, which is critical for the invasive ability of gastric cancer cells." (PMID 35008419, 2022). "Moreover, we found that Filamin A is required for Rac1 activation and the invasive ability of gastric cancer cells." (PMID 35008419, 2022). "Therefore, we theorized that FLNA could be a scaffold protein that mediates Rac1 activation via RhoGDI2 in gastric cancer cells." (PMID 35008419, 2022). "It has been found that the AC129507.1/(FLNA, TLN1) signaling axis affects the prognosis of gastric cancer through the FOCAL ADHESION pathway." (PMID 40104507, 2025). "To investigate the specific effects of ATPR on the binding of 14‐3‐3ε and filamin A, we analyzed the expression of filamin A in ATPR‐treated gastric cancer cells in the total protein level, cytoplasm, and nuclear fraction, respectively." (PMID 29862660, 2018). "This indicated that filamin A had the effect of promoting cell cycle progression and played an important role in ATPR‐induced gastric cancer cell cycle arrest." (PMID 29862660, 2018).
gastric cancer (continued). "However, under the same growth conditions, all cells grew at a similar pace, demonstrating that the reduced migration and invasion shown in RhoGDI2-expressing gastric cancer cells in response to FLNA depletion was independent of their growth rates." (PMID 35008419, 2022).
glioblastoma (7 papers, 2012 to 2024). The most malignant astrocytic tumor (WHO grade IV). "In summary, our results highlight the importance of mTORC2-FLNA lineage in glioblastoma multiforme, and suggest that FLNA is associated with mTORC2 as a new downstream target." (PMID 26134617, 2015). "Previously, we discovered that protein kinase R (PKR)‐like endoplasmic reticulum kinase (PERK) plays a role in glioblastoma stem cell (GSC) adaptation to matrix stiffness through PERK/FLNA‐dependent F‐actin remodeling." (PMID 39152526, 2024). "Recently, it has been reported that mTORC2 interacts with an actin filament crosslinking protein, Filamin A in glioblastoma cells." (PMID 38065968, 2023). "Editing levels of the Alu element sites in BRCA1 gene were increased, and those of the coding sequences in CYFIP2 and FLNA genes were reduced in glioblastoma multiforme brain tissue." (PMID 22859999, 2012). "Filamin A (FLNA), as a new downstream effector of mTORC2 to control the motility of GBM cells, functioned importantly in the movement and invasion of glioblastoma cells." (PMID 34367317, 2021). "Overall, our findings indicate that the previously identified PERK/FLNA pathway is also involved in regulating force transmission from the ECM to the actin cytoskeleton via FACs at matrix stiffnesses that are representative of normal brain and glioblastoma." (PMID 39152526, 2024). "Our functional enrichment of genes in patient tumors revealed that low expression of RND1 in glioblastoma induces an overexpression of focal adhesion proteins like extracellular matrix proteins (COL1A1 and LAMB1); integrins (ITGA5 and ITGB1); actin-binding proteins (FLNA; ACTN1) and vinculin." (PMID 30333910, 2018).
mitral valve prolapse (7 papers, 2015 to 2025). A fairly common and often benign valvular heart disorder characterized by redundancy or hooding of mitral valve leaflets so that they prolapse into the left atrium, often causing mitral regurgitation. "Of these loci, the MMVP2 locus mutation was identified as a mutation in the DCHS1 gene, and the X-linked form of mitral valve prolapse mapped to Xq28 was identified as a mutation in the FLNA gene." (PMID 33671724, 2021). "Here, we have uncovered that the first eight repeats of FlnA constitute a binding site for PTPN12/PTP-PEST and showed that the FlnA mutations associated to mitral valve prolapse that specifically target this region disrupt PTPN12/FlnA interaction." (PMID 26594644, 2015). "Mutations in the actin-binding gene Filamin-A have been linked to non-syndromic myxomatous valvular dystrophy and associated mitral valve prolapse." (PMID 26473162, 2015). "Mutations in FLNA impaired the activity of two PTPN12 substrates, which could be involved in the pathophysiology of FLNA-associated mitral valve prolapse." (PMID 33671724, 2021). "Filamin A−/− mice develop myxomatous mitral valve disease by 2 months of age, characterized by significant leaflet thickening and pathologic ECM remodeling." (PMID 26527432, 2015). "Mutations in a variety of genes that are responsible for encoding structural proteins, signaling molecules, and transcription factors—namely FBN1, FLNA, MMP2, and SOX9—have been identified as significant contributors to the pathology of mitral valve diseases." (PMID 39273357, 2024).
Thrombocytopenia (7 papers, 2014 to 2023). A reduction in the number of circulating thrombocytes. "Overall, our fibroblast experiments uncovered a membrane-associated cytoskeletal filament population uniquely affected in ACTB-AST cells, comprising β-CYA and thrombocytopenia-associated ABPs, such as α-actinin 1, NM-2A and filamin A." (PMID 30315159, 2018). "Recent evidence demonstrated that thrombocytopenia may result from mutations in filamin A." (PMID 24489676, 2014). "Moreover, mutations in cytoskeleton-associated proteins, such as FLNA, ACTN1, MYH9, or TUBB1, were identified in patients affected by proplatelet defects and thrombocytopenia." (PMID 30336771, 2018). "By labeling a few proteins, a potential abnormality could be identified or narrowed-down to a group of IPDs featured by cytoskeleton alterations (e.g., FLNA-related thrombocytopenia, FLNA-RT, TUBB1-related thrombocytopenia, TUBB1-RT, and WAS)." (PMID 32079152, 2020).
Ehlers-Danlos syndrome (6 papers, 2012 to 2022). The Ehlers–Danlos syndromes (EDS) are a clinically and genetically heterogeneous group of heritable connective tissue disorders (HCTDs) characterized by joint hypermobility, skin hyperextensibility, and tissue fragility. "A variant of PVNH, associated with FLNA mutations and Ehlers-Danlos syndrome, leads to the development of aortic dilation during early childhood." (PMID 34207234, 2021). "Secondly, we identified two cis-located FLNA mutations (c.7921C > G, p.(Pro2641Ala); c.7923delC, p.(Tyr2642Thrfs*63)) in a Bosnian patient with Ehlers-Danlos syndrome-like features such as skin translucency and joint hypermobility." (PMID 30089473, 2018). "Exon 21 nonsense mutations, frameshift and 4-shift mutations have been identified in FLNA to cause bilateral PVNH, along with Ehlers-Danlos syndrome, accompanied by minor cardiovascular malformations." (PMID 34207234, 2021). "FLNA mutations have also been associated with cutaneous manifestations such as terminal osseous dysplasia (exon 31) and the connective tissue disorder, Ehlers-Danlos syndrome (EDS)." (PMID 24278701, 2012). "Human MVP is usually classified into primary or non-syndromic, including Barlow's Disease (BD), fibro-elastic deficiency (FED) and Filamin-A mutation, and secondary or syndromic forms (typically familial), such as Marfan syndrome (MFS), Ehlers-Danlos syndrome, and Loeys-Dietz syndrome." (PMID 35656405, 2022).